MCTS1 (MCTS1 re-initiation and release factor)
Description:
Translation regulator forming a complex with DENR to promote translation reinitiation. Translation reinitiation is the process where the small ribosomal subunit remains attached to the mRNA following termination of translation of a regulatory upstream ORF (uORF), and resume scanning on the same mRNA molecule to initiate translation of a downstream ORF, usually the main ORF (mORF). The MCTS1/DENR complex is pivotal to two linked mechanisms essential for translation reinitiation. Firstly, the dissociation of deacylated tRNAs from post-termination 40S ribosomal complexes during ribosome recycling. Secondly, the recruitment in an EIF2-independent manner of aminoacylated initiator tRNA to P site of 40S ribosomes for a new round of translation. This regulatory mechanism governs the translation of more than 150 genes which translation reinitiation is MCTS1/DENR complex-dependent. Consequently, modulates various unrelated biological processes including cell cycle regulation and DNA damage signaling and repair. Notably, it positively regulates interferon gamma immunity to mycobacteria by enhancing the translation of JAK2.
Synonyms: MCT-1; MCT1; IMD118
Tractability: PROTAC: ubiquitination databases record sites on it; its protein half-life has been measured.
Gene: Protein-coding gene on chromosome X (120,594,010 to 120,621,159, forward strand). Ensembl gene ENSG00000232119.
Subcellular location: Cytoplasm
Subcellular location (Human Protein Atlas): Cytosol; Plasma membrane
Gene Ontology:
Molecular function: protein binding; ribosomal small subunit binding; RNA cap binding; translation initiation factor activity; RNA binding
Biological process: formation of translation preinitiation complex; IRES-dependent viral translational initiation; ribosome disassembly; translation reinitiation
Cellular component: cytoplasm; cytosol; translation initiation complex
Homologues: Orthologues: mouse Mcts1 (99% identical), chimpanzee MCTS1 (98% identical), dog MCTS1 (98% identical), macaque MCTS1 (98% identical), guinea pig MCTS1 (97% identical), rat Mcts1 (97% identical), tropical clawed frog mcts1 (97% identical), pig MCTS1 (96% identical), zebrafish mcts1 (94% identical), Caenorhabditis elegans C11D2.7 (64% identical), Drosophila melanogaster MCTS1 (60% identical). Paralogues in human: MCTS2 (95% identical).
Diseases named in the same sentence as MCTS1 in open-access papers:
MCTS1 is named in the same sentence as 38 diseases in open-access papers, as found by Europe PMC text mining. Sharing a sentence is not in itself a finding about the gene and the disease. The quoted sentences say what the papers report.
breast carcinoma (5 papers, 2019 to 2024). "In conclusion, this study revealed that high expression of MCTS1 is an independent adverse prognostic factor in breast cancer, and is strongly associated with aggressive clinical features and unfavorable immune infiltration." (PMID 35295953, 2022). "Third, further investigation and rigorous experimental validation are needed for both in vitro and in vivo systems to elucidate the biological functions and underlying mechanisms of MCTS1 in breast cancer." (PMID 35295953, 2022). "The hypomethylated level of MCTS1 was associated with poor prognosis in patients with breast cancer." (PMID 35295953, 2022). "MCTS1 was overexpressed in breast cancer and significantly associated with the M pathological stage, histological type, PAM50, and increased age." (PMID 35295953, 2022). "To clarify the underlying mechanisms of MCTS1 overexpression in breast cancer tissues, we also investigated the correlation between MCTS1 expression levels and methylation status using online tools." (PMID 35295953, 2022). "The study using the Kaplan–Meier method (kmplot.com) demonstrated thathigh MCTS1 expression in breast cancer samples is associatedwith a lower overall survival rate in patients compared to relatively lowerMCTS1 levels." (PMID 34377560, 2021). "In this study, we further investigated underlying mechanism of MCTS1 overexpression in breast cancer, and our data show that MCTS1 overexpression may be related to its DNA hypomethylation." (PMID 35295953, 2022). "We found that most methylation sites in the MCTS1 gene sequence were hypomethylated in breast cancer and that the degree of methylation correlated with the patient outcome." (PMID 38164286, 2024). "The correlation between MCTS1 expression and the prognosis of patients with breast cancer was calculated using the Kaplan-Meier method." (PMID 35295953, 2022). "Although our current study offers new insights into the relationship between MCTS1 expression and the prognostic value of patients with breast cancer, there are limitations that need to be considered." (PMID 35295953, 2022). "In this study, we analyzed MCTS1 expression in breast cancers using TCGA database and found that MCTS1 was highly expressed in breast cancer compared to normal tissues." (PMID 35295953, 2022). "The expression of MCTS1 was significantly higher in breast cancer samples than in normal breast tissues (p < 0.001)." (PMID 35295953, 2022). "High SOD2 expression was detected in 80% of breast cancer patients and was positively correlated with MCTS1 (p < 0.001)." (PMID 35017469, 2022). "Using the Wilcoxon rank-sum test, the MCTS1 expression levels were compared between breast cancer and normal breast tissues." (PMID 35295953, 2022). "Elevation of MCTS1 expression also increases the xenograft tumorigenicity of MCF-7 breast cancer cells by promoting angiogenesis and inhibiting apoptosis." (PMID 35295953, 2022). "Triple-negative breast cancer cells withenhanced MCTS1 expression secrete significantly more of thepro-inflammatory cytokines IL-6, MCP-1, and GM-CSF than cells with a relativelylower MCTS1 expression level." (PMID 34377560, 2021). "We found that the oncogene Multiple Copies in T-cell Malignancy 1 (MCT-1/MCTS1) expression is a new poor-prognosis marker in patients with aggressive breast cancers." (PMID 30885232, 2019). "Additionally, in our hospital cohort, breast cancer patients with high MCTS1 expression exhibited a low disease-free survival (p = 0.023)." (PMID 35295953, 2022). "Nevertheless, these results do not fully elucidate the underlying mechanism of MCTS1 in breast cancer, and the biological function and signaling pathway of MCTS1 warrant further exploration." (PMID 35295953, 2022). "The expression of MCTS1 in 80.6% (25/31) of breast cancer tissues was upregulated via IHC." (PMID 35295953, 2022).
breast carcinoma (continued). "Moreover, MCTS1 has been shown to exert oncogenic effects on breast cancer progression by affecting multiple cancer-related signaling pathways, including modulation of c-Myc translation, IL-6/IL-6R signaling pathway, and Src/p190B signaling pathway." (PMID 35295953, 2022). "Furthermore, the ROC curve indicated that MCTS1 expression had good predictive power with an area under the curve (AUC) of 0.894 (95% confidence interval [CI] = 0.877–0.911) to discriminate breast cancer tissues from normal tissues." (PMID 35295953, 2022). "MCTS1 expression may serve as a potential prognostic predictor for Luminal A, Luminal B, and triple-negative breast cancer subtypes of breast cancer." (PMID 35295953, 2022). "Multiple copies in T‐cell lymphoma‐1 (MCTS1) plays an important role in various cancers; however, its effects on patient prognosis and immune infiltration in breast cancer remain unclear." (PMID 35295953, 2022). "However, the mechanism by which MCTS1 regulates the tumorigenesis and progression of breast cancer requires further clarification." (PMID 35295953, 2022). "However, due to the heterogeneity of breast cancer, the tumorigenic effects, clinical significance, and tumor immunology of abnormal expression of MCTS1 in breast cancer are currently not fully understood." (PMID 35295953, 2022). "However, the expression levels of MCTS1 in breast cancer is unclear, since contradicting results have been reported." (PMID 35295953, 2022). "In addition, MCTS1 was highly expressed in 110 paired breast cancer tissues (p < 0.001)." (PMID 35295953, 2022). "We found that the majority of methylation sites in the DNA sequences of MCTS1 were hypomethylated in breast cancer, and the degree of methylation was correlated with patient outcomes (i.e., patients with low MCTS1 methylation had poorer overall survival than patients with high MCTS1 methylation)." (PMID 35295953, 2022). "From the Oncomine cancer microarray database, we found that MCTS1 and SOD2 expression was positively correlated in breast cancer patients (p < 0.0001)." (PMID 35017469, 2022). "Moreover, our data indicated that elevated expression of MCTS1 acts as an independent prognostic biomarker of poor OS and DSS in patients with breast cancer." (PMID 35295953, 2022).
adrenocortical carcinoma (1 paper, 2022). "The pan-cancer analysis showed that the expression of MCTS1 was highly expressed in most types of cancers, such as adrenocortical carcinoma, bladder urothelial carcinoma, cervical squamous cell carcinoma, adenocarcinoma, and cholangiocarcinoma." (PMID 35295953, 2022).
autism (1 paper, 2017). Persistent deficits in social interaction and communication and interaction as well as a markedly restricted repertoire of activity and interest as well as repetitive patterns of behavior. "The identification of DENR and MCTS1 target transcripts will serve as a basis for future studies aimed at understanding the mechanistic involvement of DENR and MCTS1 in cancer and autism." (PMID 28623304, 2017). "The non-canonical initiation factors DENR and MCTS1 have been linked to cancer and autism." (PMID 28623304, 2017).
autism spectrum disorder (1 paper, 2017). A spectrum of developmental disorders that includes autism, and Asperger syndrome. "DENR and MCTS1 are misexpressed or mutated in patients with cancer or autism spectrum disorders." (PMID 28623304, 2017). "This work will likely be a useful starting point for future studies analyzing the functional involvement of DENR and MCTS1 in cancer and autism spectrum disorders." (PMID 28623304, 2017).
cervical cancer (1 paper, 2020). A primary or metastatic malignant neoplasm involving the cervix. "Since we find DENR•MCTS1 is required for ATF4 expression in cervical cancer HeLa cells, leukemia Jurkat cells, and fibrosarcoma HT1080 cells, we postulated DENR•MCTS1 may promote ATF4 translation in many different cancers." (PMID 32938922, 2020).
COVID-19 (1 paper, 2022). A disease caused by infection with severe acute respiratory syndrome coronavirus 2. "In this study, six co-upregulated genes, RPS7, IGF1R, DICER1, ERH, MCTS1, and TNPO1, and two co-downregulated genes, FLNA and PXN, were identified from COVID-19 and thrombosis datasets." (PMID 35692833, 2022). "Based on bioinformatics analysis and previous studies, this study identified hub genes (RPS7, IGF1R, DICER1, ERH, MCTS1, TNPO1, FLNA, and PXN) that may contribute to the evaluation and treatment of COVID-19 and thrombosis." (PMID 35692833, 2022).
cutaneous melanoma (1 paper, 2015). A primary melanoma arising from atypical melanocytes in the skin. "Another oncogene MCTS1 is preserved in both the stages of cutaneous melanoma and surprisingly the gene product is under clinical trials as a drug target for small cell lung cancer." (PMID 26558755, 2015).
lung carcinoma (1 paper, 2022). "A previous study reported that high expression of MCTS1 induced the generation of ROS, which caused YY-1/EGFR/MnSOD signaling amplification and cancer cell invasion in lung cancer." (PMID 35295953, 2022).
lung squamous cell carcinoma (1 paper, 2020). "Interestingly, ASNS mRNA levels correlate with DENR•MCTS1 levels in individual cancer entities such as liver hepatocellular carcinoma (r > 0.35), lung squamous cell carcinoma (r > 0.5) and renal cancer (r > 0.49), and indeed throughout the entire TCGA pan-cancer set (r > 0.36)." (PMID 32938922, 2020).
oral cancer (1 paper, 2022). "Additionally, MCTS1 is related to the acquisition of the invasive phenotype of oral cancer cells and lung adenocarcinoma cells through the modulation of the epithelial-mesenchymal transition process, and by the regulation of E2F1 expression and the c‐Myc signaling pathway." (PMID 35295953, 2022).
osteoarthritis (1 paper, 2021). A noninflammatory degenerative joint disease occurring chiefly in older persons, characterized by degeneration of the articular cartilage, hypertrophy of bone at the margins and changes in the synovial membrane. "Among them, Ribosomal proteins were upregulated in the synovial membranes of female patients with Osteoarthritis, Carhsp1 can regulate the stability of TNF -α mRNA, they might be associated with RA, no other proteins, such as Wars, Yars, Bzw2, Mcts1 and Eif4b were reported in RA." (PMID 35006449, 2021).
renal carcinoma (1 paper, 2020). A carcinoma arising from the epithelium of the renal parenchyma or the renal pelvis. "In agreement with this, in cancer entities where ATF4 activity (assayed as ASNS mRNA levels) correlates with survival (e.g. renal cancer and liver hepatocellular carcinoma), also DENR or MCTS1 levels have prognostic value." (PMID 32938922, 2020).
Stroke (1 paper, 2023). Sudden impairment of blood flow to a part of the brain due to occlusion or rupture of an artery to the brain. "Only one gene in the time-significant module, MCTS1, negatively correlated with stroke severity." (PMID 36803375, 2023).
T-cell lymphoma (1 paper, 2022). "Malignant T cell-amplified sequence 1 (MCTS1) is an that was oncogene originally found in human T-cell lymphoma." (PMID 35692833, 2022).
tuberculosis (1 paper, 2023). A chronic, recurrent infection caused by the bacterium Mycobacterium tuberculosis. "In regions of endemic tuberculosis, in which BCG vaccination is not widely or efficiently performed, or if penetrance for BCG disease is incomplete, MCTS1 deficiency may be revealed by severe tuberculosis." (PMID 37875108, 2023).
cancer (9 papers, 2017 to 2022). A tumor composed of atypical neoplastic, often pleomorphic cells that invade other tissues. "CD147/basigin, an integral transmembrane protein belonging to the immunoglobulin superfamily, regulates glycolysis in association with monocarboxylate transporters (MCTs)-1 and -4 in cancer cells and T cells." (PMID 35008603, 2021). "These functions enable MCTS1 to play multiple roles in the occurrence and development of malignant tumors, but its mechanisms in the process of inflammation and thrombosis have not been reported and are worth further exploration." (PMID 35692833, 2022). "Ectopic expression of MCTS1 in the humanbreast cancer cells MCF-10A decreases the levels of PTEN mRNA and protein." (PMID 34377560, 2021). "This is particularly relevant if the transcript isoform that is DENR•MCTS1 dependent is the only one expressed in a cell, or the only one with cancer-relevant function." (PMID 28623304, 2017). "By identifying the DENR•MCTS1 dependent transcripts in humans, this current study enables future work aimed at understanding how these proteins affect cancer and brain function." (PMID 28623304, 2017). "Hence DENR•MCTS1 appear to promote ATF4 translation in a broad range of cancer cells." (PMID 32938922, 2020). "Hence DENR and MCTS1 appear to play a role in cancer biology and in neurobiology." (PMID 28623304, 2017). "We find that DENR•MCTS1 levels correlate with ASNS mRNA levels, a readout for ATF4 activity, across the TCGA pan-cancer set." (PMID 32938922, 2020). "We find a strong correlation between DENR•MCTS1 expression and ATF4 activity across cancers." (PMID 32938922, 2020). "So far, however, none of these pro-cancer effects of DENR•MCTS1 have been linked to direct translational targets, suggesting additional targets of DENR•MCTS1 remain to be discovered." (PMID 32938922, 2020). "Due to the role of ATF4 in cancer, as well as the role of the other DENR-target genes identified here, this may explain why DENR•MCTS1 have been identified as oncogenes." (PMID 32938922, 2020).
tumor (7 papers, 2014 to 2022). "Overexpression or copy-number gains of DENR and MCTS1, on the other hand, have been described in several tumor entities." (PMID 35115540, 2022). "Suppression of MCTS1 expression in lung and breasttumors xenografts significantly suppresses tumor development." (PMID 34377560, 2021). "DENR and MCTS1 have been identified as oncogenes in several different tumor entities." (PMID 35115540, 2022). "High expression of MCTS1 increases the level of CD44, a tumor stem cell marker." (PMID 35295953, 2022).
infectious disease (1 paper, 2023). A disorder directly resulting from the presence and activity of a microbial, viral, or parasitic agent in humans. "A search of our in-house WES and WGS (whole-genome sequencing) datasets from more than 15,000 individuals with various infectious diseases revealed no additional hemizygous pLOF variants of MCTS1." (PMID 37875108, 2023).
MCTS1 also shares sentences with these, for which no sentence is quoted: viral infection (2 papers); adenocarcinoma (1); bladder cancer (1); bladder urothelial carcinoma (1); cervical squamous cell carcinoma (1); cholangiocarcinoma (1); clear cell renal cell carcinoma (1); gastrointestinal stromal tumor (1); infiltrating ductal carcinoma (1); leukemia (1); malignant pleural mesothelioma (1); melanoma (1); monocytic leukemia (1); neurological disorders (1); prostate carcinoma (1); retinal degeneration (1); small cell lung carcinoma (1); thrombosis (1); triple-negative breast carcinoma (1); X-linked disease (1).